FOXM1 (forkhead box M1)
Diseases named in the same sentence as FOXM1 in open-access papers (continued):
Sharing a sentence is not in itself a finding about the gene and the disease.
tumor (continued). "Indeed, we find that FOXM1 inhibits CD8+ T cell tumor infiltration, in vitro T cell chemotaxis, and ex vivo CD8+ T cell killing." (PMID 38373993, 2024). "In addition, a potent FOXM1 inhibitor, thiostrepton, strongly impaired tumor cell viability in a dose-dependent manner." (PMID 38374400, 2024). "FOXM1-PROTAC suppresses tumor growth in in vivo HepG2 and MDA-MB-231 cells." (PMID 39594778, 2024). "We then sought to verify whether ABL1 could impact FOXM1 expression in tumor cell lines with FOXM1 overexpression." (PMID 39060421, 2024). "In addition, knockdown of FOXM1 significantly impaired tumor cell migration and invasion (*p < 0.05, **p < 0.01, and ***p < 0.001)." (PMID 38374400, 2024). "Moreover, FOXM1 overexpression protects tumor cells from apoptosis by facilitating DNA repair, upregulating antiapoptotic gene expression, and regulating microtubule dynamics." (PMID 39086352, 2024). "Importantly, we found a significant elevation in the number of tumor-infiltrating CD8+ T cells in the FOXM1-knockdown group." (PMID 38373993, 2024). "Concurrent treatment with cisplatin and a FOXM1 inhibitor restores cisplatin’s anti-tumor activity." (PMID 38398147, 2024). "Finally, the role of FOXM1 in suppressing anti-tumor immunity and potentially thwarting immune-based therapies is considered." (PMID 39347707, 2024). "FOXM1 gene expression is most significantly different in different stages of tumor development, and it is speculated that FOXM1 has prognostic significance in BRCA." (PMID 38608123, 2024). "Additionally, the expression levels of FOXP3, FOXO3, FOXO1, FOXA2, and FOXM1 were found to be elevated in GBM tissues from the TCGA database compared to non-tumor brain tissues, while the level of FOXQ1 was reduced." (PMID 38561331, 2024). "Moreover, compared to wild-type cells, FOXM1 Cr-Y575F MCF-7 cells exhibited significantly slower tumor growth." (PMID 39060421, 2024). "Importantly, our model highlights how a nexus of deregulation surrounding FOXM1 drives the tumor biology of AR-low TNBC." (PMID 39335162, 2024). "We found that FOXM1 mRNA and protein were highly expressed in tumor tissue with the same trend." (PMID 37976368, 2024). "Moreover, this aberrant methylation in AML results in decreased expression of miRNA-370, a tumor suppressor, and increased expression of FOXM1, a tumor-promoting factor." (PMID 38696033, 2024). "FOXM1 accelerates the development of PCa and induces tumor growth in mouse models." (PMID 38398147, 2024). "In contrast, FOXM1-targeted PROTACs might have greater anti-tumor activity as they promote protein degradation and thus fully disrupt FOXM1 functions." (PMID 38791105, 2024). "Indeed, syngeneic mouse models show that FOXM1 inhibits the infiltration of CD8+ T cells into the tumor microenvironment." (PMID 38373993, 2024). "Through our own work, we were able to demonstrate that in vivo inhibition of FOXM1 by siRNA FOXM1 injections can suppress tumor growth in TNBC tumor xenograft models in mice, suggesting that FOXM1 is a clinically significant molecular target driving the TNBC tumorigenesis." (PMID 39594778, 2024). "FOXM1 is expressed at robust levels in a variety of EwS tumor specimens and in EwS cell lines." (PMID 39524141, 2024). "In addition, FOXM1 knockdown has been reported to inhibit cell proliferation, migration, and metastasis of tumor cells." (PMID 39020302, 2024). "In an in vivo setting in mice, RCM-1 suppresses tumor growth by inhibiting FOXM1." (PMID 39594778, 2024). "Knockdown of FOXM1 impaired tumor cell viability, migration, and invasion." (PMID 38374400, 2024). "In our cohorts, significant enrichment of the genes involved in the keratinization and the formation of keratinized layers in tumor tissue (KRT5, KRT6A-C, KRT13-KRT17, KRT19) and genes associated with the regulation of cell division (FOXM1, p63) was identified." (PMID 38398111, 2024). "Knockdown of FOXM1 significantly impaired tumor cell migration and invasion." (PMID 38374400, 2024).
tumor (continued). "In addition, the high expression of mRNA in the FOXA1, FOXM1, and FOXP1 was significantly associated with tumor stage in BRCA tissues." (PMID 38608123, 2024). "miR‐370 exerts a tumor suppressor impact through targeting FOXM1 in AML cells." (PMID 38180276, 2024). "Similarly, miR-877-5p has been identified as a tumor inhibitor, with overexpression of miR-877-5p leading to suppression of tumor growth in vivo by targeting FOXM1 at both the mRNA and protein levels." (PMID 39594778, 2024). "FOXM1 is expressed only in proliferating normal and tumor cells." (PMID 39335162, 2024). "Since FOXM1‐KO markedly inhibited cell proliferation, decreased expression of FOXM1 may be an important factor in suppressed cell proliferation and tumor growth of HER3/MET‐dKO cells." (PMID 36751113, 2023). "In HepG2 and MDA-MB-231 tumor cell xenograft mice, FOXM1-PROTAC retarded tumor growth." (PMID 36733484, 2023). "In the TCGA-HCC dataset, 13 genes were identified with significant correlation with SAMD13 from the tumor group only and a total of six genes including FOXM1, JUN, JARID2, BRE, BUB1B, and PHC2 were shown to significantly predict poor overall survival in log-rank tests in HCC." (PMID 37968735, 2023). "Overexpression of FOXM1 enhanced tumor cell invasion, migration, and angiogenesis." (PMID 37759731, 2023). "FoxM1 has also been shown to be significant in various tumor initiations and progressions." (PMID 38060494, 2023). "We found hnRNP C knockdown significantly reduced OSCC proliferation, which may be attributed to the increased inclusion of FOXM1 exon 9 and expression of the tumor-suppressive FOXM1a isoform." (PMID 37759731, 2023). "The hypoxia-induced shift of EZH2 from PRC2 into FOXM1 complexes promoted tumor cell invasion." (PMID 37686402, 2023). "Notably, FOXM1 protein expression increased with advanced tumor status and lymphatic metastasis in HCC tissues." (PMID 38001498, 2023). "Taken together, our study shows that the anti-tumor effect of morin/Dox co-treatment is due to the suppression of FOXM1 and attenuation of EGFR/STAT3 signaling pathways in MDA-MB-231 TNBC cells, which suggests that morin offers a means of improving therapeutic efficacy in TNBC patients." (PMID 37242455, 2023). "FOXM1 is a vital player in the modulation of tumor magnification and metastasis." (PMID 37626655, 2023). "Additionally, FOXM1 influences Wnt/β-catenin signaling in conjunction with β-catenin and is involved in tumor malignancy." (PMID 37046727, 2023). "Additionally, FOXM1 expression was closely related to age, race, tumor status, and AJCC pathologic stage." (PMID 38001498, 2023). "Furthermore, ferritin upregulates the expression of forkhead box protein M1 (FOXM1), promoting tumor cells to undergo mitosis." (PMID 37867526, 2023). "FOXM1 is a key regulator of G2/M-specific proteins in different tumor types." (PMID 37689738, 2023). "Furthermore, the knockdown of MnSOD plus thiostrepton, a FoxM1 specific inhibitor, collaborated with isovitexin to inhibit tumor growth and reduce FoxM1 and MnSOD in nude mice bearing HCSLCs from the MHCC97H cell line." (PMID 36984844, 2023). "FOXM1 had an influence on the cell cycle of the tumor cells and the immune cell infiltration in EC." (PMID 37159818, 2023). "Therefore, we demonstrated that hnRNP C played roles in inhibiting the expression of the tumor suppressive isoform FOXM1a of oncogene FOXM1." (PMID 37759731, 2023). "Foxm1 is a well-known oncogene that drives tumor cell proliferation in solid tumors." (PMID 37526082, 2023). "Similarly, a series of studies have shown that the miR-320a inhibits tumor cell proliferation by targeting FoxM1." (PMID 38174044, 2023). "A clue to understanding this duality is the presence of a target gene for Wnt/β-catenin signaling (Hepatocyte nuclear factor 4 alpha (HNF4α)), as well as Forkhead box protein M1 (FOXM1), which influences Wnt/β-catenin signaling and is involved in tumor malignancy." (PMID 37046727, 2023).
tumor (continued). "ALKBH5 could maintain FOXM1 mRNA stability by demethylating its nascent transcripts in GSCs, leading to tumor growth." (PMID 37821870, 2023). "PAX8 may mediate some tumour-promoting effects through FOXM1 and tumour invasiveness through upregulation of FGF18." (PMID 36804485, 2023). "Likewise, RNF112 depletion readily increased tumor growth and weight, coupled with elevated expression of FOXM1 and its downstream target genes, as well as that of Ki67 and PCNA in vivo." (PMID 37288663, 2023). "Thus, circ-RNF121 regulates tumor glucose metabolism and progression via miR-1224-5p/FOXM1 axis in tumor tissues." (PMID 37208722, 2023). "However, tumor growth inhibition was better when FoxM1-shRNA was combined with IR (FoxM1-shRNA+IR: T/C%=30.5%; vs. NC p=0.00038; vs. FoxM1-shRNA p=0.020; vs. NC+IR p= 0.017)." (PMID 36860922, 2023). "Our findings reveal the tumor-promoting role of NAT10-mediated FOXM1 upregulation in LSCC, which may help to discover novel diagnostic or therapeutic targets for LSCC patients." (PMID 37948132, 2023). "Taken together, FOXM1 may contribute to regulating the tumor immune microenvironment through neutrophil infiltration in EC." (PMID 37159818, 2023). "It has been studied that FOXM1 plays a role in tumor growth and progression." (PMID 37081847, 2023). "Further analyses revealed that the activation of the FOXM1 (oncoprotein) transcription factor is a key factor in cell dedifferentiation, which enables tumor cells to acquire an epithelial-mesenchymal transition phenotype and increases the LCSC surface marker CD44." (PMID 36613925, 2022). "And FOXM1 was reported mediates CAFs’ tumor-promoting property in hepatocellular carcinoma." (PMID 36401232, 2022). "ALKBH5 could target transcription factor FOXM1 and promote the tumour proliferation of glioblastoma stem‐like cells, which could be enhanced by a nuclear lncRNA FOXM1‐AS." (PMID 35340126, 2022). "Evidence suggests CDK6 enhances tumor cell growth by regulating FOXM1." (PMID 36548336, 2022). "Lastly, we utilized the H1299 cells to establish subcutaneous tumor model and found that FOXM1 inhibitor, RCM-1, could significantly suppress the in vivo growth of tumors derived from the PHF1-deficient cells, as evidenced and compared by tumor volumes." (PMID 35945194, 2022). "Finally, in vivo assay showed that Chalcone 9X treatment repressed the expression of FOXM1, which inhibited the tumor growth of a xenograft model injected with U87 in nude mice." (PMID 35978634, 2022). "Third, the inhibition of FOXM1 significantly decreased tumor growth in mouse xenografts." (PMID 35887129, 2022). "We next evaluated FOXM1 expression according to tumor stage, gender and age." (PMID 36435510, 2022). "Western blotting of tumour tissue lysates revealed that PDK1 protein levels were significantly decreased after the knockdown of FOXM1, while the protein levels of PDK1 were restored by upregulating PDK1 expression, suggesting that the knockdown of FOXM1 can regulate the expression of PDK1 in vivo." (PMID 35656815, 2022). "FOXM1 was reported as an important cell cycle transcription factor involved in tumor progression." (PMID 35365182, 2022). "Indeed, previous studies have reported that the increased expression of FOXM1 affects tumor growth and drug resistance in various solid tumors." (PMID 35955438, 2022). "These suggest that tumor cells expressing EZH2 and FOXM1 may be pathological associated with CAFs in GC." (PMID 36401232, 2022). "FoxM1 is a common transcription factor regulating tumor cells, which is mainly involved in the regulation of cell cycle and is closely related to the abnormal proliferation and division of tumor cells." (PMID 35022030, 2022). "Moreover, the xenografts tumor model was established in vivo by subcutaneously injecting RBE cells with FoxM1 overexpression into nude mice, after which tumor volume and weight were aggrandized (p < .05)." (PMID 36301031, 2022).
tumor (continued). "As FOXM1 was closely related with tumor immune microenvironment, we sought to confirm whether it could predict response to immune checkpoint inhibitor treatment based on IMvigor 210 cohort." (PMID 36435510, 2022). "Our findings suggested that FOXM1 played a vital role in tumor immunology." (PMID 36435510, 2022). "Moreover, FOXM1 as novel component of Wnt signaling pathway and as essential in the regulation of oxidative stress, contributed to malignant transformation and tumor cell survival." (PMID 35241126, 2022). "Carfilzomib can effectively inhibit FOXM1 expression to inhibit tumor growth and could be a novel therapeutic option in patients with AFP-positive HCC who receive anti-VEGFR2 antibodies." (PMID 35955438, 2022). "Finally, a xenotransplantation experiment was performed to analyze the role of FOXM1 in tumor progression." (PMID 35887129, 2022). "We evaluated the clinicopathological characteristics of the FOXM1-high and -low HCC cases, and FOXM1-high HCC was significantly associated with high serum AFP levels, poorly differentiated histological findings, large tumor size, and a high frequency of microscopic portal vein invasion." (PMID 35955438, 2022). "It should be pointed out that further studies are warranted to determine the functional activities of FAM64A and FOXM1 using HNSCC patient-derived cells, which are very important to reflect the close interactions between FAM64A and FOXM1 in the tumor microenvironment." (PMID 35538067, 2022). "Moreover, studies have found that FOXM1 promotes tumor metastasis by inducing EMT in tumor cells in HCC and PC." (PMID 35614040, 2022). "Moreover, IHC staining demonstrated that the staining intensity of FOXM1 in xenograft tumor tissues was significantly lower in the FAM64A depletion group, and dramatically higher in the FAM64A overexpression group." (PMID 35538067, 2022). "In addition, RA treatment downregulated the oncogenic transcription factor forkhead box M1 (FOXM1) and targeted genes involved in tumor growth and abnormal cell proliferation." (PMID 36359936, 2022). "Demethylation of FOXM1 increased both FOXM1 expression and tumor growth." (PMID 36250017, 2022). "Collectively, these findings suggest that TST‐mediated FOXM1 inhibition could abrogate immune evasion and effectively reduce tumor growth." (PMID 35975458, 2022). "FoxM1 is involved in tumor invasion, angiogenesis, and metastasis." (PMID 35884976, 2022). "Of note, RCM-1 could also inhibit protein levels and nuclear localization of β-catenin, abolishing interactions between β-catenin and FOXM1 in cultured tumor cells and in vivo." (PMID 35945194, 2022). "DZY-3, (camptothecin), which inhibits DNA replication in proliferating tumor cells, has been used as an antitumor drug for many years, and this study was able to propose a new mechanism for its antitumor action, by demonstrating that it inhibits FOXM1." (PMID 36505747, 2022). "Likewise, the clonogenic and tumor-initiating potential of shFAM64A-treated cells was restored by overexpression of FOXM1." (PMID 35538067, 2022). "In addition, western blotting results showed that the expression level of FOXM1 protein was lower in the tumor tissues formed by FAM64A-knockdown cells, and the opposite results were observed when FAM64A was overexpressed." (PMID 35538067, 2022). "FoxM1 is strongly expressed in a variety of neoplasms and is related to poor clinical outcomes." (PMID 36301031, 2022). "In fact, FoxM1 has a strong regulatory effect on the metabolic recombination of tumor cells." (PMID 35022030, 2022). "Together, these results show that DEPDC1 stimulated tumour development by FOXM1 regulation." (PMID 36072787, 2022). "The tumor xenografted mice model was used for evaluating FOXM1-PROTAC therapeutic response in vivo." (PMID 36171633, 2022). "Therefore, the roles of ERG-cg27071152-MTURN and FOXM1-cg19212949-PTPR in different tumor stages and in LUAD progression were explored." (PMID 36550923, 2022).
tumor (continued). "Finally, our in vivo experiments revealed that inhibition of hsa_circ_0042823 notably reduced tumour growth in mouse model of LSCC through regulating miR-877-5p/FOXM1 axis." (PMID 34124974, 2021). "Also, shRNA-mediated FOXM1 knockdown led to the diminished proliferation and reduced cell migration in three-dimensional culture and xenograft tumor models." (PMID 35012286, 2021). "To assess whether the three tumor suppressor genes are involved in FOXM1/miR-552 axis induced cell migration, we transfected a mixture of three siRNAs into PANC1 cells, and observed a strong migration phenotype relative to the control group." (PMID 33867818, 2021). "Forkhead box protein M1 (FOXM1) is an oncogene regulating tumor growth and metastasis." (PMID 33971889, 2021). "A literature search revealed that FOXM1 is a miR-149 target, indicating that FOXM1 might contribute to the tumor-inducing function of GACAT3." (PMID 34496842, 2021). "Additionally, ALKBH5 was demonstrated to contribute to LUAD progression by increasing the Forkhead box M1 (FOXM1) protein expression to induce hypoxia-mediated tumour proliferation." (PMID 34638933, 2021). "However, when extrapolating our findings into a wide tumor context, we found that FOXM1-dependent BMF repression appears disrupted in anoikis-resistant cells." (PMID 34035233, 2021). "In LSCC, FoxM1 was shown to be elevated and served as a tumor promoting gene." (PMID 33882027, 2021). "In brief, these observations demonstrate a strong reliance of tumor cells on FOXM1." (PMID 34740322, 2021). "Importantly, our findings disclose BMF levels as predictive of tumor response to antimitotic chemotherapy, with only higher levels supporting combination therapy of FOXM1 inhibitors with antimitotics." (PMID 34035233, 2021). "Recent data have shown that miR-802 as a tumor suppressor could control proliferation of MCF-7 cells through expression regulation of FOXM1." (PMID 33541259, 2021). "In addition, FoxM1 gives cancer cells self-renewal properties by increasing the side population (SP) cells and forms larger and more numerous tumor spheres." (PMID 33588867, 2021). "It was reported that Foxm1 directly interacts with Mat1a, which is a tumor suppressor in the liver." (PMID 34539442, 2021). "E2F and FoxM1, two transcription factors regulate Plk1 expression 33, 34, thus they could be closely related to Plk1-dependent tumor development." (PMID 34646387, 2021). "New studies indicated that FOXM1 participated in drug resistance, canceration and metastasis of tumors 52-54, so inhibiting FOXM1 may be a promising tactic for tumor treatment." (PMID 33391456, 2021). "However, the underlying molecular mechanisms by which UA regulates the Akt/FOXM1 signaling pathway and enhances the anti-tumor efficacy of PTX in ESCC are not fully understood." (PMID 34768915, 2021). "Our literature identified the mechanism of FOXM1 in tumor genesis." (PMID 33391456, 2021). "Our data demonstrated that TS irreversibly crosslinks PRX3 through its active site Cys residues to form inactive covalent dimers, leading to increased mROS levels, reduced FOXM1 expression and anti-tumor activity in both in vitro and in vivo malignant mesothelioma (MM) tumor models." (PMID 33498547, 2021). "Taken together, our findings suggest that miR-23b-5p acted as a tumor suppressor role in HCC progression by targeting FOXM1 and may serve as a potential novel biomarker for HCC diagnosis and prognosis." (PMID 33723252, 2021). "Targeting FOXM1 would kill tumor cells in a selective way, which could avoid the toxicity to normal cells." (PMID 34880209, 2021). "Hsa_circ_0042823 may promote proliferation, migration, invasion and tumour growth in LSCC through miR-877-5p/FOXM1 axis." (PMID 34124974, 2021). "We monitored tumor growth to explore whether FOXM1 could reverse the effect of PINT87aa overexpression in HCC in vivo and found a larger tumor volume in the FOXM1 overexpression group." (PMID 33754036, 2021).